AVL9 (AVL9 cell migration associated)
Description:
Functions in cell migration.
Synonyms: KIAA0241
Tractability: Antibody: UniProt predicts a signal peptide or a membrane-spanning region. PROTAC: ubiquitination databases record sites on it; its protein half-life has been measured.
Gene: Protein-coding gene on chromosome 7 (32,495,426 to 32,588,726, forward strand). Ensembl gene ENSG00000105778.
Subcellular location: Recycling endosome; Membrane
Subcellular location (Human Protein Atlas): Endoplasmic reticulum
Gene Ontology:
Biological process: cell migration
Cellular component: recycling endosome; cytoplasm; membrane
Genetic constraint (gnomAD): Loss-of-function variants: 27 observed, 45.92 expected, observed/expected ratio (o/e) 0.59, 90% interval 0.43 to 0.81. The upper end of that interval is the gene's LOEUF score, 0.81, which puts it in group 3 of 6, group 1 being the genes least tolerant of losing a copy. Missense variants: 561 observed, 635.45 expected, observed/expected ratio (o/e) 0.88, 90% interval 0.82 to 0.95. Synonymous variants: 246 observed, 237.86 expected, observed/expected ratio (o/e) 1.03, 90% interval 0.93 to 1.15.
Homologues: Orthologues: chimpanzee AVL9 (99% identical), macaque AVL9 (99% identical), dog AVL9 (93% identical), mouse Avl9 (92% identical), pig AVL9 (91% identical), rabbit AVL9 (90% identical), rat Avl9 (87% identical), guinea pig AVL9 (84% identical), tropical clawed frog avl9 (73% identical), zebrafish avl9 (63% identical), Drosophila melanogaster CG11178 (35% identical), Caenorhabditis elegans T26A5.6 (31% identical).
Diseases named in the same sentence as AVL9 in open-access papers:
AVL9 is named in the same sentence as 11 diseases in open-access papers, as found by Europe PMC text mining. Sharing a sentence is not in itself a finding about the gene and the disease. The quoted sentences say what the papers report.
lung adenocarcinoma (5 papers, 2021 to 2025). A carcinoma that arises from the lung and is characterized by the presence of malignant glandular epithelial cells. "Among these model mrlncRNAs, lncRNA of ALMS1-IT1 can accelerate tumor malignant progression (e.g., lung adenocarcinoma) via AVL9-mediated activation of the cyclin-dependent kinase pathway." (PMID 37312123, 2023). "Luan and colleagues recently reported that ALMS1-IT1 promoted the malignant progression of lung adenocarcinoma through AVL9-mediated activation of the cyclin-dependent kinase pathway." (PMID 35350786, 2022). "AVL9 can be used as an independent prognostic factor for lung adenocarcinoma based on the TCGA database." (PMID 33683834, 2021). "Experimental evidence indicates that the interaction between ALMS1‐IT1 and AVL9 may contribute to the malignant advancement of Lung Adenocarcinoma (LUAD) by influencing the cyclin‐dependent kinase pathway." (PMID 39334527, 2024).
colorectal cancer (3 papers, 2014 to 2022). A primary or metastatic malignant neoplasm that affects the colon or rectum. "High expression of AVL9 was closely correlated with M status, stages and poor prognosis of colorectal carcinoma (CRC) patients." (PMID 34991461, 2022). "To investigate the role of AVL9 in CRC, we analyzed AVL9 expression at mRNA level in colorectal carcinoma based on TCGA database." (PMID 34991461, 2022). "We report here that three genes, AVL9, DENND5A and NUPL1, which are recurrently deleted in colorectal cancer, all contribute to epithelial morphogenesis." (PMID 25621300, 2014). "The current study revealed that AVL9 mRNA expression was significantly increased in colorectal carcinoma tissue compared to corresponding non-cancer tissue based on TCGA database." (PMID 34991461, 2022).
lung carcinoma (3 papers, 2022 to 2026). "Previous studies have shown that upregulation of ALMS1-IT1 can promote lung cancer progression by mediating AVL9 activation of the cell cycle protein-dependent kinase pathway." (PMID 35464855, 2022). "We generated an AVL9 knockout (KO) line using CRISPR-Cas9 in A549 lung cancer cells." (PMID 41542567, 2026). "Among the many predicted targets, seven genes (SOX4, ZEB2, AVL9, PTPN9, RAB22A, ITGB8 and SIX1) that have been reported to play an oncogenic role in lung cancer were further analyzed." (PMID 35287543, 2022).
clear cell renal cell carcinoma (1 paper, 2021). "For example, high expression of AVL9 in clear cell renal cell carcinoma accelerates cell migration." (PMID 33683834, 2021).
cyst (1 paper, 2014). A sac-like closed membranous structure that may be empty or contain fluid or amorphous material. "The “filled-lumen cysts” have a single lumen per cyst, but inside the lumen often harbor apoptotic cells, nuclear fragments and other cellular debris, and for those of AVL9-knockdown clones, sometimes live cells as well." (PMID 25621300, 2014).
gastric cancer (1 paper, 2021). A primary or metastatic malignant neoplasm involving the stomach. "Furthermore, in patients with gastric cancer, the high expression of AVL9 leads to poor prognosis." (PMID 33683834, 2021).
small cell lung carcinoma (1 paper, 2022). Small cell lung cancer (SCLC) is a highly aggressive malignant neoplasm, accounting for 10-15% of lung cancer cases, characterized byrapid growth, and early metastasis. "There are studies have shown that in small cell lung cancer, ALMS1-IT1 regulates AVL9 by adsorbing miRNAs, and participates in the regulation of cell cycle-related CDK pathways, thereby affecting tumor progression." (PMID 35299954, 2022).
cancer (3 papers, 2014 to 2026). A tumor composed of atypical neoplastic, often pleomorphic cells that invade other tissues. "Accumulating evidences implicated that AVL9 played a vital role in human cancers, but it’s biological function and mechanism in CRC remain unclear." (PMID 34991461, 2022). "AVL9, a novel protein associated with establishing and maintaining epithelial cell polarity, has been reported that the loss of cell polarity acted as a hallmark of epithelial cancers, indicating that epithelial polarity is involved in cancer tumorigenicity and migration." (PMID 34991461, 2022). "The predicted catalytic residue of Avl9 is important for cancer cell migration in culture, indicating functional conservation and physiological relevance across eukaryotes." (PMID 41542567, 2026). "Human AVL9 was previously shown to play a role in cultured cancer cell migration and we have recapitulated these findings using both wound healing and transwell migration assays." (PMID 41542567, 2026). "The results showed that AVL9 expression was substantially higher in cancer tissues (n=286) than that in normal tissues (n=41) (P<0.05)." (PMID 34991461, 2022). "This screen identified a high-confidence prediction between Arf1 and Avl9, a conserved protein of unknown function reported to play roles in secretion and cancer cell migration." (PMID 41542567, 2026). "In current study, data from the cancer genome atlas (TCGA) database showed that expression of AVL9 was observably increased in cancer tissue compared to non-cancer tissue, as was consistent with our results of IHC analysis." (PMID 34991461, 2022). "AVL9, DENND5A and NUPL1 are among the cancer driver candidate genes previously identified via dog-human comparison, and may function in epithelial cell polarity as indicated by bioinformatics analysis." (PMID 25621300, 2014).
tumor (3 papers, 2022 to 2023). "AVL9 expression was significantly upregulated in tumor tissues than that in matched normal tissues both at mRNA and protein levels." (PMID 34991461, 2022). "Similarly, higher expression of AVL9 was distinctly related to M status (P = 0.001) and stages (P = 0.048), rather than other clinicopathological characteristic, such as gender, age, tumor size, differentiation, T classification and N status." (PMID 34991461, 2022). "Next, in order to detect AVL9 expression at protein level, we analyzed the tissue microarray containing 83 tumor samples and 83 non-tumor samples." (PMID 34991461, 2022).
AVL9 also shares sentences with these, for which no sentence is quoted: atherosclerosis (1 paper); non-small cell lung carcinoma (1).